RAD21 (RAD21 cohesin complex component)
Diseases named in the same sentence as RAD21 in open-access papers (continued):
Sharing a sentence is not in itself a finding about the gene and the disease.
tumor (55 papers, 2008 to 2025). "This enabled us to identify the core genes associated with tumor stemness induced by tumor intrinsic variations and finally we selected four genes: RAD21, EXOSC4, CSE1L and RAE1." (PMID 40406120, 2025). "Univariate analysis data indicate that in ERBB2-high cohort mRNA expression of RAD21 low was significantly associated with tumor grade (p = 0.011)." (PMID 37474724, 2023). "In contrast, RAD21 low mRNA showed significant association with low tumor grade in ERBB2-high cohort." (PMID 37474724, 2023). "Increased Rad21 gene dosage is associated with Rad21 mRNA expression and unfavorable tumor characteristics." (PMID 29797792, 2018). "In the current study, we found that nuclear RAD21 was increased in HCC tissues compared with adjacent non-tumor tissues, and higher RAD21 levels were associated with shorter OS of HCC patients." (PMID 28434945, 2017). "Our findings support a growing body of evidence suggesting that cohesion defects and aberrant RAD21 expression are pathogenic events that contribute to tumor development." (PMID 23962039, 2013). "From a tumorigenic perspective altered RAD21 expression is associated with a number of tumor types – over-expression is associated with advanced tumor stage and grade, enhanced invasion and metastasis, and the acquisition of multidrug resistance." (PMID 23962039, 2013). "Collectively, these data strongly suggest that RAD21 over-expression may be a pathogenic event in a variety of tumor types, including HL." (PMID 23962039, 2013). "Intriguingly, we identified two stemness-associated genes, RAD21 and CSE1L, driven by intrinsic tumor variations." (PMID 40406120, 2025). "Among these drivers, RAD21 and CSE1L were found to be tumor intrinsic copy number variation-driven factors associated with tumor stemness and tumor evolution." (PMID 40406120, 2025). "Fusobacteria high regions were also associated with increased DNA damage on a protein level as detected by staining of tumor sections with an antibody detecting RAD21, a DNA double-strand break repair protein." (PMID 38709233, 2024). "The results showed that the level of RAD21 mRNA in the tumor tissues from 23 NSCLC patients was higher than that in paracarcinoma tissues." (PMID 38378967, 2024). "To further confirm the oncogenic role of RAD21 in vivo, we established a xenograft tumor mouse model by subcutaneously injecting control and RAD21-KD H1299 or H1650 cells into the right dorsal flanks of nude mice." (PMID 38378967, 2024). "When compared with the oe-LINC00858 + sh-NC treatment, the volume and weight of tumor after treatments of oe-LINC00858 + sh-RAD21 and oe-LINC00858 + sh-PCNP were lower." (PMID 35468892, 2022). "This critical role of the RAD21–YAP/TEAD4 complex in HGSOC tumor biology hints at its potential to be targeted therapeutically in HGSOC." (PMID 36201246, 2022). "The results showed that Rad21 depletion significantly suppressed tumor growth in immune-competent C57BL/6 mice bearing B16-OVA tumor." (PMID 36201246, 2022). "Together, these findings demonstrated that overexpression of RAD21 in tumor cells suppressed T cell activation and cytotoxic T cell activity." (PMID 36201246, 2022). "Relative to the treatment of oe-LINC00858 + sh-NC, the expression levels of RAD21 and PCNP, and phosphorylation levels of STAT3 and STAT5 in the tumor tissues were lower after treatment of oe-LINC00858 + sh-RAD21." (PMID 35468892, 2022). "We further demonstrated in murine syngeneic tumor models that RAD21 ablation potentiated anti–PD-1 efficacy with increased intratumoral CD8+ T cell effector activity." (PMID 36201246, 2022).
tumor (continued). "Univariate analysis using the logistic regression model showed that the high expression of PTTG2 and RAD21 was significantly associated with tumor relapse, while low expression of MAD1L1 was associated with tumor relapse (P values < 0.05 for all cases)." (PMID 32596342, 2020). "The palindromes that are associated with oncogenes, such as RAD21, NBN and KMT2A, were found to have changed significantly in the tumor samples." (PMID 33298903, 2020). "Despite the rescue of ALT phenotypes, tumor cells in rad21+/− fish exhibit an increase in DNA damage foci, probably due to a reduction in double-strand breaks repair efficiency." (PMID 33266037, 2020). "We found that the expression levels of CDK1, HDAC2 and RAD21 were increased in tumor tissues compared with the adjacent normal tissues." (PMID 28434945, 2017). "The expression levels of the core genes RAD21, HDAC2, and CDK1 were increased in HCC tissues compared with adjacent non-tumor tissue, and their expression levels were associated with the OS of HCC patients." (PMID 28434945, 2017). "Most relevant to the current study is the finding that RAD21 is frequently amplified in two of the four tumor types evaluated." (PMID 23962039, 2013). "Future studies will be required to elucidate the specific mechanism(s) by which RAD21 and other cohesion genes contribute to the development of various tumor types such as HL." (PMID 23962039, 2013). "This is further supported by the positive correlation between RAD21 gene expression and protein expression, as assessed by immunohistochemistry in matched tumor samples." (PMID 22537934, 2012). "The systematic and mechanistic investigation of Rad21's role in the radiosensitivity of different normal tissues will be important for understanding the radiation responses in both tumours and normal tissues." (PMID 20711430, 2010). "Overexpression was verified for Thymidylate Synthase, VG5Q, Chk1, NQO1 and RAD21, where tumour cells were positive in most cases." (PMID 19662092, 2009). "RAD21 blockade improves response to anti–PD-1 therapy and suppresses tumor progression." (PMID 36201246, 2022). "Furthermore, IHC analysis confirmed that Rad21 ablation enhanced the level of tumor-infiltrating CD8+ T cells." (PMID 36201246, 2022). "Importantly, RAD21 ablation induced T cell activation and enhanced antitumor efficacy of anti–PD-1 in multiple murine syngeneic tumor models." (PMID 36201246, 2022). "In vivo experiments indicated that RAD21 promoted tumor growth." (PMID 35860572, 2022). "The Rad21 subunit of the Cohesin complex has been shown to act as a tumor suppressor and promoter of pro-inflammatory myeloid polarization in the hematopoietic system, while acting to preserve stemness and prevent differentiation of progenitor cells in the epidermis." (PMID 32022682, 2020). "In view of the role of RAD21 in increasing HR activity, tumor RAD21 status may be particularly relevant in patients being considered for PARP-inhibitor therapy." (PMID 22537934, 2012). "Furthermore, the PCNA, PRKDC and RAD21 module is important to DNA repair as it also helps to suppress tumours." (PMID 23002138, 2012). "However, little is known about the roles of Rad21 in tumor progression." (PMID 28831167, 2017). "Thus, of the four members of the cohesin complex members, RAD21 is emerging as a lead candidate that may predict tumor behavior and therapeutic resistance, but it may also represent a candidate therapeutic target." (PMID 23962039, 2013). "RAD21 upregulation may be an early event that occurs before tumor invasion." (PMID 22537934, 2012).
tumor (continued). "In a recurrent tumor in the parapharyngeal space of the patient discussed in our report, ARID1A G2087R, PRKR1A F200fs∗6, and RAD21 amplification were identified as disease-relevant alterations by genetic testing." (PMID 40777560, 2025). "These combined approaches enabled the identification of six tumour suppressor driver genes—namely BAP1, CREBBP, FAT1, NCOA6, RAD21 and UBR5—as regulators of the DDR and maintenance of chromosomal stability in NSCLC." (PMID 39738653, 2024). "We initially compared the total expression levels of ERBB2, RAD21, RAD50 and BARD1 mRNA in normal and tumor bladder tissues with bioinformatics analyses using the TCGA database (Cohort one)." (PMID 37474724, 2023). "The effects of RAD21 were evaluated through Cell Counting Kit-8 (CCK8), wound-healing, and invasion assays in vitro and the tumor growth in vivo." (PMID 35860572, 2022). "Telomere qPCR analyses using genomic DNA extracted from RAS and rad21;RAS tumor samples and from control brains revealed an increase of telomere content heterogeneity in the RAS samples, but similar-to-control telomere content in rad21;RAS tumors." (PMID 33266037, 2020). "Somatic alterations in cohesion-related genes (e.g. SMC1A, SMC3, STAG2, RAD21, etc.)have however, been identified in a large number of CIN tumor types." (PMID 23962039, 2013). "Our results were consistent with those of the meta-analysis such that GSN, SPTBN1, SFRP1 and MAF were down-regulated in most tumor samples with respect to their matched non-tumor samples whereas COX6C, RAD21, GSPT1, NME1 and PTTG1 were up-regulated." (PMID 19116033, 2008). "Hence, we suspect that the amplification of RAD21 promotes immune escape by activating B7-H4 expression in OV malignant cells, whereas CSE1L potentially influences tumor progression by stimulating the expression of VEGF." (PMID 40406120, 2025). "RAD21, BOP1, POLR2E, and PRKDC were mainly expressed in tumor cells, RIPK2 was mainly expressed in monocytes, MAP2K2 was mainly expressed in tumor cells and macrophages, NBN was mainly expressed in macrophages and monocytes, and GPX4 was mainly expressed in tumor cells and T cells." (PMID 36212155, 2022). "RAD21 expression correlated with larger tumor size (P = 0.012) and lymph node involvement (P < 0.001), but not with tumor grade (P = 0.328), age (P = 0.815), HER2 status (P = 0.564) or ER status (P = 0.054)." (PMID 21255398, 2011). "Even though RAD21 has been previously noted for its copy number amplification helping with tumor immune avoidance and lessening the efficacy of immunotherapy, we also found that CSE1L amplification can facilitate tumor cell invasion through the activation of JAK-STAT and VEGF signaling pathways." (PMID 40406120, 2025). "In addition, rad21;RAS tumor cells exhibited a decrease of mean signal intensity, telomere length heterogeneity, and ultra-long telomeres compared to RAS tumor cells." (PMID 33266037, 2020). "In light of these findings we believe that aberrant RAD21 expression, particularly over-expression in HDLM-2 and perhaps underexpression in L-540 (and L-428), has a role in the development and progression of various tumor types, which we have expanded to include HL." (PMID 23962039, 2013). "However, STAG2 and RAD21 have not been reported to affect tumor metastasis directly." (PMID 35371307, 2022).
tumor (continued). "In the tumor tissues following oe-LINC00858 + sh-PCNP treatment, RAD21 expression was not altered while PCNP expression and phosphorylation levels of STAT3 and STAT5 were decreased in those following oe-LINC00858 + sh-NC treatment." (PMID 35468892, 2022). "The effect of genomic changes on RAD21 expression appears to be independent of BRCA status and intrinsic tumor subtype." (PMID 22537934, 2012).
infection (6 papers, 2018 to 2024). The state of being infected such as from the introduction of a foreign agent such as serum, vaccine, antigenic substance or organism. "Consistent with ectopic ISC differentiation, loss of Rad21 inhibited ISC proliferation in response to infection by the mild enteropathogen Erwinia carotovora carotovora 15 (Ecc15), as assessed by the quantification of phospho-Histone H3+ cells in the gut." (PMID 32022682, 2020). "Accelerated DENV2 replication damaged host DNA as mutant infection was dependent on host DNA damage repair factors, namely RAD21, EID3 and NEK5." (PMID 36514984, 2022). "We found that the viral production was significantly lower, up to an order of magnitude in SMC1 and Rad21 knockdown cells 16 h after initial infection." (PMID 33485391, 2021). "SMC1 and Rad21 could promote HSV-1 replication compartment development at the early infection stage, and the knockdown of SMC1 and Rad21 resulted in a decrease of HSV-1 replication and viral copy number." (PMID 33485391, 2021). "Compared with mock infection, changes in the binding of CTCF and RAD21 and histone modifications after IAV infection and IFN-β treatment were finally measured by the proportions of intervals having different binary values." (PMID 39202349, 2024). "We knocked down SMC1 or Rad21 in BJ and HeLa cells, followed by HSV-1 infection at an MOI of 0.1, and measured HSV-1 genome replication at a series of time points within 10 h post-infection through monitoring the viral genome copy number with qPCR." (PMID 33485391, 2021).
heart diseases (2 papers, 2017 to 2019). "RAD21, the third most significant gene, is related to memory formation (through genomic structure of BDNF and Arc) as well as to heart diseases." (PMID 29322921, 2017).
malformation syndrome (2 papers, 2018 to 2022). "CdLS, an autosomal dominant (NIPBL, SMC3, and RAD21) or X-linked (SMC1 and HDAC8) malformation syndrome, represents the best characterized cohesinopathy." (PMID 36467423, 2022). "The best characterized cohesinopathy is CdLS, an autosomal dominant (NIPBL, SMC3, and RAD21) or X-linked (SMC1A and HDAC8) malformation syndrome." (PMID 36467423, 2022).
cardiovascular disease (1 paper, 2022). "We constructed an mRNA–miRNA–lincRNA ceRNA interaction network centered on miR-22-3p and used the starBase v2.0 and miRWalk databases to predict eight related transcription factors associated with cardiovascular disease, namely, CTCF, JUN, JUND, NFATC1, NFE2L2, RAD21, RELA, and TAL1." (PMID 36105099, 2022).
connective tissue disorder (1 paper, 2020). A disease involving the connective tissue. "Among the top disease subnetworks designated by IPA, MYC CNVs were associated with skeletal/muscular disorders and RAD21 CNVs were associated with connective tissue disorders." (PMID 32859084, 2020).
haematopoietic neoplasms (1 paper, 2021). "RAD21 protein is a structural component of the cohesin complex and SNVs in RAD21 have been reported in haematopoietic neoplasms." (PMID 35178361, 2021).
RAD21 also shares sentences with these, for which no sentence is quoted: chronic atrial and intestinal dysrhythmia (3 papers); Intellectual disability (3); schizophrenia (3); Warsaw breakage syndrome (3); gastric cancer (2); genetic disorder (2); Langer-Giedion syndrome (2); lymph node metastases (2); neuropathy (2); osteosarcoma (2); adenocarcinoma (1); angiosarcoma (1); atherosclerosis (1); autism spectrum disorder (1); B cell lymphoma (1); benign tumor (1); bladder urothelial carcinoma (1); breast (1); breast invasive lobular carcinoma (1); cervical squamous cell carcinoma (1); chronic lymphocytic leukemia (1); chronic myeloid leukemia (1); colorectal adenocarcinoma (1); developmental disabilities (1); diaphragmatic hernia (1); ductal carcinoma (1); endometriosis (1); esophageal cancer (1); familial breast cancers (1); fibrosarcoma (1).
A further 38 diseases each share a sentence with RAD21 in 1 paper.